ZNF865 (zinc finger protein 865)
Description:
May be involved in transcriptional regulation.
Tractability: PROTAC: UniProt records ubiquitination sites on it; ubiquitination databases record sites on it; its protein half-life has been measured.
Gene: Protein-coding gene on chromosome 19 (55,605,638 to 55,617,269, forward strand). Ensembl gene ENSG00000261221.
Subcellular location: Nucleus
Subcellular location (Human Protein Atlas): Nucleoli; Nucleoplasm
Gene Ontology:
Molecular function: DNA-binding transcription factor activity; RNA polymerase II cis-regulatory region sequence-specific DNA binding
Biological process: regulation of transcription by RNA polymerase II
Cellular component: nucleus
Genetic constraint (gnomAD): Loss-of-function variants: 0 observed, 2.71 expected, observed/expected ratio (o/e) 0, 90% interval 0 to 1.08. That is too few expected variants to judge how well the gene tolerates losing a copy. Missense variants: 1,268 observed, 1,241.5 expected, observed/expected ratio (o/e) 1.02, 90% interval 0.97 to 1.07. Synonymous variants: 732 observed, 604.8 expected, observed/expected ratio (o/e) 1.21, 90% interval 1.14 to 1.29.
Homologues: Orthologues: dog ZNF865 (92% identical), mouse Zfp865 (88% identical), pig ZNF865 (88% identical), rat Znf865 (88% identical), guinea pig ZNF865 (84% identical), tropical clawed frog znf865 (53% identical), zebrafish si:dkeyp-69b9.6 (24% identical), zebrafish znf865 (23% identical), Drosophila melanogaster CG10631 (19% identical), Drosophila melanogaster CG11902 (18% identical), Drosophila melanogaster CG11696 (10% identical). Paralogues in human: ZNF667 (16% identical), ZNF671 (14% identical), ZNF710 (12% identical), ZNF366 (12% identical), ZNF662 (10% identical), ZNF783 (8% identical), ZNF212 (7% identical).
Diseases named in the same sentence as ZNF865 in open-access papers:
ZNF865 is named in the same sentence as 5 diseases in open-access papers, as found by Europe PMC text mining. Sharing a sentence is not in itself a finding about the gene and the disease. The quoted sentences say what the papers report.
esophageal cancer (2 papers, 2023 to 2024). A primary or metastatic malignant neoplasm involving the esophagus. "ZNF865 was involved in transcriptional regulation and affected in prognosis, immunity, and treatment of esophageal cancer." (PMID 37989982, 2024). "Results indicate that ZNF91, and ZNF586 were upregulated in esophageal cancer tissue than adjacent tissue, whereas ZNF502, ZNF865, ZNF106, and ZNF225 was downregulated." (PMID 37013470, 2023).
prostate carcinoma (1 paper, 2021). A carcinoma that arises from epithelial cells of the prostate gland. "For now, we have no info about the potential roles of ZNF865 in the progression of prostate cancer." (PMID 34209090, 2021).
ZNF865 also shares sentences with these, for which no sentence is quoted: cancer (1 paper); endometriosis (1); Neurodevelopmental delay (1).